RBMY1E (RNA binding motif protein Y-linked family 1 member E)
Description:
RNA-binding protein which may be involved in spermatogenesis. Required for sperm development, possibly by participating in pre-mRNA splicing in the testis.
Tractability: No criterion of Open Targets' tractability assessment is met for any kind of drug.
Gene: Protein-coding gene on chromosome Y (21,903,618 to 21,918,042, reverse strand). Ensembl gene ENSG00000242389.
Subcellular location: Nucleus
Subcellular location (Human Protein Atlas): Nucleoplasm; Nucleoli
Gene Ontology:
Molecular function: protein binding; nucleic acid binding; RNA binding
Biological process: mRNA splicing, via spliceosome
Cellular component: spliceosomal complex; nucleus
Homologues: Orthologues: macaque RBMY (34% identical), rat Rbmy1j (34% identical), mouse Rbmyf9 (32% identical), mouse Rbmyf2 (32% identical), mouse Rbmyf3 (32% identical), mouse Rbmy (32% identical), mouse Rbmyf1 (32% identical), mouse Rbmyf5 (32% identical), mouse Rbmyf6 (32% identical), mouse Rbmyf7 (32% identical), mouse Rbmyf8 (32% identical), mouse Rbmyf4 (17% identical). Paralogues in human: RBMY1D (99% identical), RBMY1A1 (99% identical), RBMY1B (99% identical), RBMY1F (99% identical), RBMY1J (99% identical), RBMX (48% identical), RBMXL1 (46% identical), RBMXL2 (38% identical), RBMXL3 (31% identical), CIRBP (16% identical), MSI1 (14% identical), RBM3 (14% identical), and 24 more.
Diseases named in the same sentence as RBMY1E in open-access papers:
RBMY1E is named in the same sentence as 3 diseases in open-access papers, as found by Europe PMC text mining. Sharing a sentence is not in itself a finding about the gene and the disease. The quoted sentences say what the papers report.
cryptorchidism (1 paper, 2019). The failure of one or both testes of a male fetus to descend from the abdomen into the scrotum during the late part of pregnancy. "Our findings implicate Y-chromosomal genes, including USP9Y, UTY, TXLNGY, RBMY1B, RBMY1E, RBMY1J and TSPY4, some of which are known to be important for spermatogenesis, in the curative hormonal treatment of cryptorchidism-induced infertility." (PMID 31171972, 2019).
RBMY1E also shares sentences with these, for which no sentence is quoted: Azoospermia (1 paper); Infertility (1).